ERBB2 (erb-b2 receptor tyrosine kinase 2)
Diseases named in the same sentence as ERBB2 in open-access papers (continued):
Sharing a sentence is not in itself a finding about the gene and the disease.
cancer (continued). "The TIMER2.0 revealed the expression of ERBB2 and immune cell infiltration in specific cancers and their correlation with prognosis in different types of cancers." (PMID 36172165, 2022). "In one study, oleic acid was shown to suppress the overexpression of a well-known oncogene, HER2 (erbB-2), which plays a key role in the progression of several human cancers." (PMID 35889426, 2022). "Receptor tyrosine-protein kinase erbB-2 (ERBB2) expression is a critical factor for the prognosis of various cancers." (PMID 36172165, 2022). "To illustrate that ERBB2 gene enrichment leads to a poor prognosis in some cancers but a good prognosis in other cancers, we detailed the gene alteration frequency data for a systematic comparison of ERBB2 gene structural variants across pan-cancers." (PMID 36172165, 2022). "Most anti-cancer ER intrabodies targeting cell surface receptors (human Il-2 receptor, ErbB-2, TLR2) were constructed from hybridoma clones." (PMID 35892709, 2022). "In conclusion, here we propose a provocative therapy based on the combinatorial administration of a growth factor, namely NRG4, in combination with anti-ERBB2 antibodies as a novel anti-cancer strategy based on specific activation of ERBB4-ERBB4 homodimers." (PMID 35664762, 2022). "ErbB2 is thought to be an oncogene and has become a target for a number of targeted anti-cancer drugs." (PMID 35909446, 2022). "The wilcoxon test was performed to determine the differential expression of ERBB2 in various cancer types." (PMID 35990657, 2022). "Various studies have shown that serum ErbB2/HER2 concentration elevation is a specific marker for a variety of cancers, such as breast cancers, ovarian, bladder, salivary gland, endometrial, pancreatic, and non-small-cell lung cancer." (PMID 35322023, 2022). "The proportion of ERBB2-low cancers was higher among patients with hormone receptor–positive MBC than those with hormone receptor–negative disease (4083 patients [33.0%] vs 588 patients [21.0%])." (PMID 36107428, 2022). "Abnormal amplification of the ERBB2 proto-oncogene has been condemned as a critical factor resulting in the tumorigenesis of various types of cancers and is related to poor survival outcomes." (PMID 36172165, 2022). "MARCKS-related protein (MARCKSL1) is a widespread, highly conserved membrane-associated protein whose hyperexpression promotes cell proliferation via the ErbB2-mediated signalling pathway and facilitates angiogenesis and growth in carcinoma cells in vivo." (PMID 35719407, 2022). "Amplification of ERBB2 is well-described in many kinds of solid cancer and has been established as an important actionable target in multiple cancer types." (PMID 33828969, 2021). "In oncogene mutated cancers like KRASG12D-driven PDAC (Pancreatic Ductal Adenocarcinoma) and MYC/KRAS or MYC/ERBB2-ablated breast cancer, cancer cells predominantly rely on OXPHOS for energy production." (PMID 34557865, 2021). "The ERBB2 gene (also called HER2) is a well-described oncogene that is commonly amplified or overexpressed in human cancers." (PMID 34209587, 2021). "The ERBB2 somatic mutations found in cancer samples are usually located in the kinase domain (KD) or hotspots in the extracellular domains (ECD) and have been shown to activate ERBB2 signaling." (PMID 34209587, 2021). "In some preclinical studies, NK-92 cells were transduced with second-generation CARs containing a composite CD28-CD3ζ signaling domain to target ErbB2-positive cancer cells." (PMID 33752707, 2021). "It was found that ErbB2 is overexpressed in some types of human tumors with an epithelial origin and it is thought that it has a role in cancer development and progression." (PMID 33752707, 2021).
cancer (continued). "ECD-dependent ErbB2 mRNA export is functionally relevant in the context of overexpressed ECD in cancer cells, which is supported by our observations that KD of ECD dramatically reduced the oncogenic traits." (PMID 33941617, 2021). "All cancer cell lines except Caco-2 (3.4%) showed a high interaction level with ErbB2, as ErbB2 is another major interacting partner of EGFR in addition to EGFR itself." (PMID 33603128, 2021). "Both 1st and 2nd line treatments of HER2 positive cancers are aimed at targeting the HER2 receptor directly, thereby strongly limiting the treatment options of HER2/ErbB2 inhibition resistant invasive cancers." (PMID 33939112, 2021). "One of the earliest therapeutics developed based on genetic alterations was trastuzumab for cancers carrying genomic amplification of a region of chromosome 17 containing the ERBB2/HER2 gene, which led to better outcomes than first-line chemotherapy." (PMID 34359640, 2021). "Relations between several MAPK signaling proteins and EGFR to ERBB2 signaling are also among those observed in the vast majority of cancer types." (PMID 34179843, 2021). "Here, we applied this concept to HER2+ cancers, as ERBB2 overexpression is known to characterize aggressive tumors and its interplay with eADO has also been demonstrated." (PMID 34948316, 2021). "Elucidation of the contribution of germline ERBB2 variants to MPN and possibly other cancer types will require functional studies." (PMID 34209587, 2021). "Our study provides insight into the right strategies to treat ERBB2-positive cancer via targeting autophagy." (PMID 33801244, 2021). "Among the identified significant enriched pathways, we found regulation of transcription, mRNA splicing, pathways in cancer and signaling by ErbB2/4." (PMID 34944912, 2021). "Recently, molecular analysis has confirmed that ST6GAL1 decreases the sensitization of cancer cells to trastuzumab-induced cytotoxicity through directly enhancing α2,6-sialylation of ErbB2, which results in the increased activation of both ErbB2 and EGFR RTKs." (PMID 34745942, 2021). "Several cancer-associated genes have been identified on chromosome 17q, including PPM1D, EME1, BRCA1, ERBB2, NF1, RAD51C, BRIP1 and BIRC5." (PMID 34885154, 2021). "Among cancer‐critical genes (defined in the COSMIC Cancer Gene Census), recurrent high‐level amplifications were found only of ERBB2 in two patients, while EGFR and the cell cycle genes CDK6, CCND2, and CCND3 were amplified in one patient each." (PMID 33325154, 2021). "While there is a wealth of knowledge concerning the effects of Tz on ERBB2+ cancer cells and on EV biogenesis, structure, and functions, less is known about possible modifications induced by Tz on EVs released by ERBB2+ cells." (PMID 33809102, 2021). "The effectiveness of this cytokin was also tested in human gastric epithelial (HGE-20) cancer cells, where septins and the receptor tyrosine kinase ErbB2 were highly expressed." (PMID 31955380, 2021). "MIEN1 is present specifically in the ERBB2 amplicon and is fundamental in regulating the migration and invasion of cancer cells." (PMID 34066014, 2021). "ERBB2 is also overexpressed in subsets of patients with a variety of other cancers, including gastric, non-small cell lung, colon, bladder, and biliary cancers." (PMID 33997928, 2021). "ErbB2 is a prominent representative of the epidermal growth factor receptors that mainly attract attention as oncogenic drivers and therapeutic targets in cancer." (PMID 32591879, 2021). "That is why the research and development of new therapeutics for ErbB2+ cancer treatment is an important task for scientists around the world." (PMID 34944558, 2021). "Translocation of ERBB2 into mitochondria has been reported in cancer cells that overexpress the receptor." (PMID 34685621, 2021).
cancer (continued). "In contrast, regions more H3K9ac-enriched in HeLa contained genes involved in cell–cell adherens junction (FE 2.0, P = 9.4 × 10–20) and pathways in cancer (FE 1.5, P = 9.9 × 10–8), including oncogenes such as ERBB2, WNT5A and BRAF." (PMID 33542322, 2021). "In past years therapy has evolved, especially for cancers with known oncogenic driver mutations such as EGFR, ALK, ROS1 and BRAF, or newly discovered NSCLC drivers such as MET, RET, NTRK1/2/3 and ERBB2 (HER2)." (PMID 34685711, 2021). "EGFR/BRAF, EFRF/KRAS, KRAS/ERBB2 demonstrated a mutually exclusive relationship, consistent with the recent evidence from cancer genomic studies which demonstrated that driver genes are often mutated in a mutually exclusive manner." (PMID 35186718, 2021). "ERBB2 is another important therapeutic target of the epidermal growth factor receptor family in the treatment of malignant tumors." (PMID 35070983, 2021). "Overexpression of Cdc25A significantly increased ErbB2 mRNA and protein levels in cancer cells, while sorafenib treatment or PKM2-S37D overexpression reduced these levels." (PMID 34743185, 2021). "The ErbB family members ErbB1 (epidermal growth factor receptor (EGFR)) and ErbB2 (human epidermal growth factor receptor 2 (HER2)) are intensively studied receptor tyrosine kinases (RTKs) with fundamental roles in cancer." (PMID 33128042, 2021). "While the effects of Trastuzumab on ERBB2 cancer cells are well known, those on the extracellular vesicles (EVs) released from these cells are scarce." (PMID 33809102, 2021). "Amplification of ERBB2 is a potential therapeutic target in other cancer types, including lung, bladder, endometrial, ovary, colorectal, esophageal, and bile duct cancers." (PMID 33710417, 2021). "The pharmacological inhibition of ErbB3 by a monoclonal antibody sensitizes ErbB2-overexpressing cancer cells and xenografts to a tyrosine kinase inhibitor, showing that ErbB3 is an important cancer therapeutic." (PMID 34572289, 2021). "For example, in patient BC09, multiple subclones were derived from an actionable ERBB2 amplification in both lesions with only 55.4 and 68.2% of cancer cells." (PMID 33920370, 2021). "ErbB3 is a member of EGFR family of receptor tyrosine kinases, which serves as a homolog to EGFR (ErbB1) and HER2 (ErbB2) and plays an important role in cancers." (PMID 34400880, 2021). "Here, we performed a post-transcriptional screen for frequently amplified cancer genes demonstrating that ERBB2/Her2 overexpression was able to augment the post-transcriptional effects." (PMID 34535639, 2021). "Several CAR-engineering approaches capable of targeting the ErbB2-positive cancers are now in development process." (PMID 33752707, 2021). "ERBB2 modulates the proliferation and metastasis of cancer cells through the activation of PI3K/AKT and MAPK/ERK pathways." (PMID 34765599, 2021). "Together with the effects of these amplified oncogenes on the reporter data, the ERBB2/EGFR/AKT pathway appears to be a major player in ARE-mediated post-transcriptional regulation in relevant cancers." (PMID 34535639, 2021). "In the present study, we aimed to compare targeted NGS-based ERBB2 CN estimation with HER2 IHC or FISH for breast and other cancer types, and to define the accurate ERBB2 CN therapeutic cutoff value." (PMID 33710417, 2021). "The aberrant activation of receptor ERBB2 in human cancers promotes tumorigenesis through the stimulation of AKT signaling." (PMID 33802957, 2021). "The abnormal expression of ERBB2 is closely related to the occurrence and development of a variety of malignant tumors, including GC." (PMID 33953786, 2021). "Highly significant expression changes in 17 known cancer genes such as ERBB2, KRAS and SMAD4 were observed by analyzing the RNA sequencing data of 116 EACs, showing a correlation with a high degree of chromosomal instability." (PMID 34503107, 2021).
cancer (continued). "By labeling with a heterodimeric peptide ligand, the gold nanoparticles specifically target overexpression of EGFR and ErbB2 by the cancer cells." (PMID 34832857, 2021). "ERBB2 expression was increased in EVs from HER2-positive cell lines or in blood-derived EVs of cancer patients." (PMID 33995103, 2021). "Regarding specific cancer-associated genes, the CYT-high subgroup had more CNAs, including gains in NF1, CDK12, ERBB2, RARA, MDM4 and MYC; and losses in BRCA1, CD274 and APC." (PMID 34316699, 2021). "HER2 (ERBB2/neu) and HER3 (ERBB3) are receptor tyrosine kinases implicated in cancer invasion and metastasis." (PMID 33467681, 2021). "The pathway analysis found enrichment for regulation of transcription, mRNA splicing, pathways in cancer and ErbB2/4 signaling." (PMID 34944912, 2021). "For example, overexpression of the EGFR family member ERBB2/HER2/NEU, which activates the PI3K/Akt pathway, is associated with platinum resistance in ovarian, NSCLC, and HNSCC cancer patients." (PMID 34645978, 2021). "Human epithermal growth factor receptor 2 (HER2/ErbB2) is the protein that promotes the growth of various cancer cells and leads to poor prognosis." (PMID 34666670, 2021). "Overexpression of Cdc25A in cancer cells reversed these changes, while knockdown of ErbB2 blocked the effects of Cdc25A overexpression." (PMID 34743185, 2021). "Specifically, the silencing of the MAP kinase MK2 in SKBR3 cells led to a reduction in the abundance of phosphorylated ZFP36/TTP, indicating this pathway’s involvement in ERBB2-amplified cancer cells." (PMID 34535639, 2021). "Lapatinib has been reported to inhibit the growth of cancer via the ERBB2/AKT/mTOR and RAF/MEK/ERK signaling pathways." (PMID 34459788, 2021). "On the basis of the specific structure, MUC4 was suggested to modulate HER2/ERBB2 signaling and play a critical role in cancer." (PMID 34336844, 2021). "The ARE-mRNA cluster of ERBB2 (160 genes) found here is significantly over-represented when compared to the overall ERBB2-positive expressed genes and comprises many genes that are important in several cancer processes." (PMID 34535639, 2021). "It has to be highlighted that the effect on ErbB2 expression is very likely to have a strong impact on cancer cell growth." (PMID 34561494, 2021). "As a member of the epidermal growth factor receptor (EGFR) family, tyrosine kinase receptor 2 (ERBB2) is important to the research of cancer biology and cardiac function and development." (PMID 35071383, 2021). "For these reasons EGFR and its preferred heterodimer partner, HER2/ERBB2, became popular targets of anti-cancer therapies." (PMID 34206026, 2021). "In ERBB2-driven cancers, ERBB3 enhances cancer progression, usually by PI3K/AKT pathway activation, by functioning as a heterodimer partner." (PMID 34843459, 2021). "Patients with ERBB2+/HR+ cancers are treated with a combination of anti-HR and anti-ERBB2 treatment." (PMID 33670942, 2021). "ErbB2 has also been incorporated in CAR-engineered NK-92 cells to be evaluated in cancer experiments." (PMID 33752707, 2021). "Newer insights into ErbB2 biology are required to open avenues to promote more effective and durable responses to targeted therapy of ErbB2-driven breast and other cancers." (PMID 34439093, 2021). "Lapatinib was able to normalize the prolonged mRNA half-life in ERBB2-amplified cancer cells for several selected ARE-mRNAs, which confirms the ARE reporter assay data." (PMID 34535639, 2021). "Cancer and proliferation-related genes such as Wnt7b, S100a14, and Erbb2, were downregulated by thermal ablation in directly-treated tumors (A-T) 1 week after ablation, and to a lesser extent, 24 h after mechanical HIFU (M-T) compared to control (NTC)." (PMID 33441763, 2021). "Another important aspect is alterations present in different cancer types with the potential of favorable responses in many patients, illustrated in our study by a large number of studies of ERBB2 and BRAF inhibitors." (PMID 35008297, 2021).
cancer (continued). "The observation of ERBB2 targeting by miRNA-7 instead of EGFR1 observed in cancer cells suggests unique cell specific mechanisms of regulation." (PMID 34759299, 2021). "Second, three patients showed exon 20 insertion mutations in ERBB2 (p.A775_G776insYVMA), for which a response to pan-HER kinase inhibitors has been reported in various types of cancer." (PMID 34638295, 2021). "Ongoing clinical trials are investigating the effect of neratinib (SUMMIT trial; NCT01953926) and afatinib (NCI-MATCH; NCT02465060) in patients with ERBB2-mutant cancers." (PMID 34257600, 2021). "Frequently detected genetic alterations (>5% in >5 samples across all studies) in GBC for which targeted therapies are available in other cancer types included mutations in ATM, ERBB2, and PIK3CA, and ERBB2 amplifications." (PMID 34771420, 2021). "These ERBB2/HER2 mutations are associated with resistance to lapatinib but are sensitive to neratinib, highlighting the importance of treating HER-mutated cancers with the appropriate HER-targeted drugs." (PMID 34499316, 2021). "The Neu oncogene induces tumors that exhibit uniform luminal histology, require CDK4 and cyclin D1 for transformation and are thought to reflect the ErbB2 subtype of human cancer." (PMID 34736527, 2021). "The epidermal growth factor receptor (EGFR) family member erb-b2 receptor tyrosine kinase 2 (ERBB2) is overexpressed in many types of cancers leading to (radio- and chemotherapy) treatment resistance, whereas the underlying mechanisms are still unclear." (PMID 33801244, 2021). "Off note, treatment of an ErbB2 driven mouse model with an inhibitor of EZH2 revealed strong synergy with anti-ErbB2 targeted therapy which highlights the importance of EZH2 in several cancers and emphasizes its clinical relevance." (PMID 33235291, 2021). "Specifically, ERBB2 overexpressing cancers are treated with monoclonal antibodies such as trastuzumab and pertuzumab, which block endogenous ligand binding to ERBB2 receptors." (PMID 33670942, 2021). "Surprisingly, CB2 receptors were seen within 91% of ErbB2-positive carcinoma tissues, suggesting an association between the expression of CB2 and ErbB2." (PMID 34205169, 2021). "The choice of the initial profile was guided by biology: dual inhibitors of EGFR and ErbB2 are regarded as an advantageous treatment option for several carcinomas, whereas BRAF is a common undesired anti-target." (PMID 33530327, 2021). "It is well known that overexpression of ERBB2 contributes to the metastatic cascade in many types of cancers including ESCC." (PMID 33042286, 2020). "Accordingly, the anti-cancer effects of multiple HSP90 inhibitors have been experimentally demonstrated either as monotherapies or in combinations with other ErbB2-targeting agents." (PMID 32327714, 2020). "These include well-known cancer-associated genes, such as CCND1 (25 tumors), CDK4 (25 tumors), MDM2 (23 tumors), SETDB1 (23 tumors), ERBB3 (11 tumors), ERBB2 (11 tumors), MYC (10 tumors) and MYCN (five tumors)." (PMID 32025003, 2020). "ErbB2 drives these cancers, and they are often treated with ErbB2 neutralizing anti-ErbB2 antibodies trastuzumab and pertuzumab." (PMID 33023655, 2020). "The overexpression of human epidermal growth factor receptor 2 (ERBB2) promotes the differentiation and proliferation of cancer cells, which is recognized as one of the key causes of GC and seriously affects the prognosis of GC patients." (PMID 32020871, 2020).